PDPN (podoplanin)
Diseases named in the same sentence as PDPN in open-access papers (continued):
Sharing a sentence is not in itself a finding about the gene and the disease.
Lipedema (3 papers, 2020 to 2022). Disorder of adipose tissue characterized by symmetric and bilateral enlargement of the lower extremities due to abnormal deposition of subcutaneous fat often in obese women. "The expression levels of other lymphatic-related genes, such as podoplanin (PDPN), PROX-1, lymphatic-vessel endothelial hyaluronan receptor 1 (LYVE1), and C-C motif chemokine ligand 21 (CCL21), were similar in lipedema fat tissue compared to healthy controls." (PMID 36551837, 2022). "In this regard, three lymphatic vessel markers (podoplanin/PDPN, LYVE-1 and PROX-1) were used to characterize the size and number of lymphatic vessels in paraffin tissue sections from lipedema and control patients." (PMID 32616854, 2020). "No significant changes were observed for most of the common lymphatic markers, namely PDPN, PROX-1, LYVE-1, CCL21 but a 1.9-fold (P = 0.02) increase was observed in the expression of VEGFR-3 in lipedema in comparison to the control." (PMID 32616854, 2020). "Interestingly, in areas of subdermal blood vessel networks and identified as CD31 positive and podoplanin negative, a higher number of macrophages (CD68+) is visible in lipedema skin, which may indicate blood vessels with altered permeability." (PMID 35625899, 2022).
liver fibrosis (3 papers, 2019 to 2023). "Recently, a study revealed that platelets can bind with podoplanin via c-type lectin-like receptor 2 (CLEC-2) and that activated platelets promote liver protection and inhibit liver fibrosis after cholestatic liver injury." (PMID 35668355, 2022).
metastasis (3 papers, 2014 to 2021). The spread or migration of cancer cells from one part of the body (where they first appeared) to another. "An association between low levels of PDPN in the tumor cells with the presence of lymphatic invasion and lymph node metastasis was found, suggesting that low expression of PDPN might be a risk marker of tumor recurrence and invasion of lymphatic system." (PMID 27313335, 2016). "We identified TNC and PDPN to be significant markers of occult node metastasis." (PMID 33420101, 2021).
nasopharyngeal carcinoma (3 papers, 2019 to 2024). A carcinoma arising from the nasopharyngeal epithelium. "Endogenous PDPN expression in C8161 cells and nasopharyngeal cancer cell line CNE-2 was detected using western blot and flow cytometry." (PMID 31208371, 2019). "The role of podoplanin (PDPN) in nasopharyngeal carcinoma (NPC) is still unknown." (PMID 31321241, 2019).
odontogenic tumor (3 papers, 2014 to 2019). "Similarly, the participation of podoplanin in local invasion of odontogenic tumors was reinforced by our previous findings." (PMID 25480364, 2014). "Interestingly, the keratocystic odontogenic tumors presented strong membranous podoplanin and cytoplasmic ezrin expression, which correspond to the activated forms of both proteins." (PMID 25480364, 2014). "Therefore, the authors hypothesised that PDPN is involved in extracellular matrix remodelling and cell growth in odontogenic tumours." (PMID 24527067, 2014). "Although the odontogenic cell motility induced by podoplanin may be dependent on its interaction with the activated ezrin, the connection between both proteins has not previously been studied in odontogenic tumors." (PMID 25480364, 2014).
oropharyngeal squamous cell carcinomas (3 papers, 2022 to 2025). "Podoplanin overexpression has also been associated with poorer prognosis in oral and oropharyngeal squamous cell carcinomas, including reduced overall survival, disease-specific survival, and disease-free survival, as well as a higher frequency of nodal metastasis (N+ status)." (PMID 41228241, 2025). "Tissue blocks of biopsy-proven Oropharyngeal Squamous Cell Carcinoma were subjected to Immunohistochemistry (IHC) for evaluating the expression of p16, e-cadherin, vimentin and podoplanin." (PMID 41146851, 2025). "This study aimed to investigate the spatial distribution and clinical significance of podoplanin expression in the metastatic lymph nodes of oropharyngeal squamous cell carcinomas (OPSCCs)." (PMID 35256682, 2022).
pancreatic adenocarcinoma (3 papers, 2022 to 2025). "In various malignancies, including breast, lung, and pancreatic adenocarcinomas, where PDPN is absent from tumor cells, the expression of PDPN in CAFs has been associated with metastasis, poor patient outcomes, and reduced overall survival." (PMID 40842027, 2025).
peritonitis (3 papers, 2015 to 2025). Inflammation of the peritoneum (tissue that lines the abdominal wall and covers most of the organs in the abdomen). "This is consistent with previous findings that blockade of PDPN leads to an increased cytokine storm and bacterial proliferation in mice with peritonitis." (PMID 39903516, 2025). "We assessed the relevance of crosslinking podoplanin using rCLEC-2-Fc during ongoing peritonitis induced by LPS on the accumulation of inflammatory macrophages in the inflamed peritoneum." (PMID 34163489, 2021). "Beside the role of CLEC-2-podoplanin in thrombosis, deletion of platelet-CLEC-2 or haematopoietic-podoplanin increases the cytokine storm and bacterial growth and spreading during caecal ligation and puncture-mediated peritonitis." (PMID 34163489, 2021). "In case with acute peritonitis, mesothelial cells did not express podoplanin." (PMID 26366298, 2015).
preeclampsia (3 papers, 2018 to 2024). Preeclampsia is a hypertensive disorder of pregnancy that is characterized by new-onset hypertension with proteinuria presenting after 20 weeks of gestation, and depending on mild or severe forms may initially present with severe headache, visual disturbances, and hyperreflexia. "We examined CuZn–SOD expression and distribution associated with nephrin and podoplanin expression in shed podocytes from women with preeclampsia." (PMID 29981208, 2018). "As a paradox, several previous studies of PDPN expression in the human placenta were reported to be performed, mostly associated with pathologic conditions such as preeclampsia or chronic venous disease, but its expression in normal human full-term placenta was not described precisely." (PMID 38920982, 2024). "The interest in the PDPN expression in human placenta continuously increased based on several papers which reported its importance in the preeclampsia mechanism." (PMID 38920982, 2024). "In the acute placental inflammation group, podoplanin immunoreactivity was similar to that in the control group, whereas in the preeclampsia group, podoplanin expression was higher than in all other groups." (PMID 31578434, 2019). "In the CVS cells of the preeclampsia group, podoplanin immunoreactivity was more homogeneous and stronger than in all other groups, especially in the distal villi." (PMID 31578434, 2019). "In addition, our results suggest that high-level podoplanin expression in CVS cells contributes to the development of clinical symptoms of preeclampsia." (PMID 31578434, 2019). "In cases of IUGR and preeclampsia, podoplanin immunoreactivity was strong in areas where reticular stroma could be observed in chorionic villi." (PMID 31578434, 2019). "Therefore, the development of pharmacological agents that modulate the activity of podoplanin would provide a new option for the treatment of preeclampsia." (PMID 31578434, 2019). "Podoplanin expression in preeclampsia has been the subject of several studies." (PMID 31578434, 2019). "To test the hypothesis that oxidative stress contributes to kidney podocyte injury in preeclampsia, we specifically examined expression and distribution of antioxidant CuZn‐SOD with nephrin and podoplanin in shed podocytes from women with preeclampsia." (PMID 29981208, 2018). "Our results implicate podoplanin expression in CVS cells in two important placental pathologies, preeclampsia and hydatiform mole, with expression of the protein differing significantly in these tissues compared to normal placental tissues at the same gestational week." (PMID 31578434, 2019). "Similarly, expression of podoplanin and CuZn‐SOD were also reduced or lost in shed podocytes from preeclampsia compared with AB 8/13 differentiated podocytes." (PMID 29981208, 2018).
small cell lung carcinoma (3 papers, 2015 to 2019). Small cell lung cancer (SCLC) is a highly aggressive malignant neoplasm, accounting for 10-15% of lung cancer cases, characterized byrapid growth, and early metastasis. "Cancer-associated fibroblasts (CAFs) expressing podoplanin (PDPN) are a favorable prognosticator in surgically resected small cell lung cancer (SCLC)." (PMID 25909164, 2015). "However, in tumors such as colorectal carcinomas and small-cell lung cancer (SCLC), podoplanin expression in CAFs is considered a favorable prognostic marker." (PMID 30736372, 2019).
Stroke (3 papers, 2021 to 2025). Sudden impairment of blood flow to a part of the brain due to occlusion or rupture of an artery to the brain. "In animal models, podoplanin neutralization has had a significant impact on acute cardiovascular events, including stroke and infarct sizes." (PMID 41465476, 2025).
testicular tumors (3 papers, 2016 to 2025). "The expression of the POSTN and PDPN genes at the mRNA level was found in 100% (n = 28) of the analysed testicular tumours." (PMID 41361308, 2025). "Analysing POSTN and PDPN expression in neoplastic cells of testicular tumours, we observed that their expression was significantly lower in LCTs than in SCTs and SEMs, both in percentage of positive cells and intensity." (PMID 41361308, 2025). "The upregulation of the POSTN and PDPN genes observed in canine testicular tumours raises important questions about the fundamental regulatory mechanisms involved." (PMID 41361308, 2025). "The expression of POSTN and PDPN has been demonstrated for the first time in canine spontaneous testicular tumours, indicating their participation in the process of testicular carcinogenesis in dogs, as was already suggested for PDPN in human testicular tumours." (PMID 41361308, 2025). "The higher expression of POSTN and PDPN observed in SCTs and SEMs, compared to LCTs, may reflect the different characteristics of testicular tumours in the dog and could have prognostic and therapeutic implications that encourage further investigation involving a larger number of samples." (PMID 41361308, 2025). "The reappearance of PDPN expression in testicular tumours, observed in humans and also in dogs within this study, suggests that the protein, whose role is not yet fully understood, may be involved in the process of cell dedifferentiation that is part of carcinogenesis." (PMID 41361308, 2025).
tongue cancer (3 papers, 2012 to 2019). A malignant neoplasm affecting the tongue. "The association between LpMab-23-recognizing cancer-type PDPN expression and clinical/pathological features were analyzed on 60 patients with stage I and II tongue cancer treated with transoral resection of the primary tumor." (PMID 29765527, 2018). "In the immunohistochemical analysis of differences between D2-40 and LpMab-23 in tongue cancer tissue, the reaction to lymphatic vessels was observed in D2-40 but not in LpMab-23, suggesting that LpMab-23 is specific for cancer-type PDPN." (PMID 29765527, 2018). "We report that the reactivity of a novel monoclonal antibody LpMab-23 for human cancer-type podoplanin (PDPN) is a predictor for a poor prognosis of tongue cancer." (PMID 29765527, 2018). "The aim of this study is to investigate the usefulness of LpMab-23, a unique mAb for cancer-type PDPN, as a predictor for a poor prognosis of early stage tongue cancer." (PMID 29765527, 2018). "Podoplanin expression was investigated in intratumoral and peritumoral tissues of patients with tongue cancer." (PMID 24551781, 2012). "Furthermore, LpMab-23-recognizing cancer-type podoplanin could be a novel predictor for a poor prognosis of early stage tongue cancer." (PMID 30997422, 2019).
type 2 diabetes (3 papers, 2019 to 2025). "This suggests that PDPN, a glycoprotein known for its roles in cell migration, adhesion, and lymphatic vessel development, is also intricately involved in the inflammatory processes associated with Type 2 Diabetes Mellitus (T2DM)-induced brain injury." (PMID 39911382, 2025).
alopecia (2 papers, 2013 to 2019). Hair loss usually from the scalp. "In men, alopecia was associated with a significant (P < 0.001) increase in the amounts of versican+ stromal cells and human podoplanin+ lymphatic vessels." (PMID 24455724, 2013). "In conclusion, our results suggest an unanticipated role of PDPN in the HF cycle, with potential implications for therapeutic strategies to treat alopecia." (PMID 31335913, 2019).
aortic stenosis (2 papers, 2021 to 2025). Aortic valve stenosis is a aortic valve disease caused by the incomplete opening of the aortic valve. "The overall impact of podoplanin on aortic stenosis likely depends on the delicate balance between lymphangiogenesis and angiogenesis." (PMID 40076529, 2025). "This imbalance may be more pronounced in severely calcified valves compared to sclerotic valves, suggesting a potential role for podoplanin as a biomarker for severe aortic stenosis." (PMID 40076529, 2025). "These factors may limit the specificity and clinical utility of plasma podoplanin as a biomarker for aortic stenosis and warrant further investigation." (PMID 40076529, 2025). "The pulmonary tissues of a patient, born with HLHS, aortic arch hypoplasia, and valvular anomalies and developed postoperative chylothorax after aortic arch, and supravalvar aortic stenosis repair was stained for PROX1, PODOPLANIN, VEGFR2, and VEGFR3." (PMID 34590077, 2021).
Ascites (2 papers, 2023 to 2026). Accumulation of fluid in the peritoneal cavity (between the layers of the peritoneum that lines the abdomen). "To summarize, we report here that an increased number of dilated LVs, characterized by PDPN expression in the D2-biopsies, are a characteristic feature of patients with decompensated cirrhosis and ascites and PDPN score serves as a valuable predictor of 3-month mortality." (PMID 37304826, 2023).
basal cell carcinoma (2 papers, 2022 to 2025). A carcinoma involving the basal cells. "Mean of podoplanin expression in histological subtypes of basal cell carcinoma." (PMID 36505148, 2022).
breast angiosarcoma (2 papers, 2018 to 2022). A malignant vascular neoplasm arising from the breast. "They observed, specifically, in radiation-induced breast angiosarcomas a concrete deregulation in the marker genes of the lymphatic endothelial cells, such as podoplanin (PDPN), PROX1, VEGFR3, and endothelin receptor A (EDNRA), which was probably induced through chronic oxidative stress." (PMID 35885529, 2022). "The deregulation of marker genes, including podoplanin (PDPN), prospero homeobox 1 (PROX-1), vascular endothelial growth factor 3 (VEGFR3) and endothelin receptor A (EDNRA), suggests that the radiation-associated breast angiosarcomas developed from radiation-stimulated lymphatic endothelial cells." (PMID 29515789, 2018). "Interestingly, radiation-induced breast angiosarcomas have their own transcriptome signature, with a panel of deregulated marker lymphatic genes such as PROX1, podoplanin, VEGFR3, and EDNRA, which allows its discrimination from primary breast angiosarcomas." (PMID 35885529, 2022). "Interestingly, the dysregulation of PROX1, along with PDPN, VEGFR3, and EDΝRA, seems to play a pathogenetic role in the development of post-radiotherapy breast angiosarcomas, which, through the identification of those specific genes, present a discriminating genetic “signature”." (PMID 35885529, 2022).
carcinoma in situ (2 papers, 2007 to 2021). "The role of podoplanin expression in carcinoma in situ also has to be addressed." (PMID 17179989, 2007).
cardiac hypertrophy (2 papers, 2020 to 2021). "Although VEGFCc156s treatment enhanced podoplanin-positive lymphatic vessel growth in the heart at this timepoint, it did not alleviate cardiac hypertrophy in angiotensin II-infused mice." (PMID 33200983, 2020).
cardiomyopathy (2 papers, 2014 to 2023). A disease of the heart muscle or myocardium proper. "Some other genes may be responsible for cardiomyopathy as PDPN, and CASZ1." (PMID 36369750, 2023).
cholangiocarcinoma (2 papers, 2022 to 2024). A carcinoma that arises from the intrahepatic biliary tree (intrahepatic cholangiocarcinoma) or from the junction, or adjacent to the junction, of the right and left hepatic ducts (hilar cholangiocarcinoma). "Correlation analysis indicated that the CNV of PDPN was positively correlated with its mRNA level in 10 of the 33 tumor types, especially in low-grade glioma (LGG; r = 0.57) and cholangiocarcinoma (CHOL; r = 0.44)." (PMID 36032075, 2022).
chondrosarcoma (2 papers, 2009 to 2017). A malignant cartilaginous matrix-producing mesenchymal neoplasm arising from the bone and soft tissue. "In their series, podoplanin was expressed strongly (10/10) by chondrosarcomas." (PMID 28439237, 2017). "Archival material from three extraskeletal myxoid chondrosarcomas, five chordomas, five chondromyxoid fibromas, five chondroblastomas and 25 chondrosarcomas was stained with antibodies against osteonectin, bcl-2, cox-2, actin, calponin, D2-40 (podoplanin), mdm-2, CD117 (c-kit) and YKL-40." (PMID 19594492, 2009).
Cirrhosis (2 papers, 2010 to 2023). A chronic disorder of the liver in which liver tissue becomes scarred and is partially replaced by regenerative nodules and fibrotic tissue resulting in loss of liver function. "Our study reports that patients with cirrhosis have a significantly increased number of lymphatic channels characterized by PDPN and VEGF-C immunostaining and PDPN and LYVE1 expression in the D2-biopsy lysates." (PMID 37304826, 2023). "Here, we studied LVs in duodenal (D2)-biopsies of liver cirrhosis patients and investigated the prognostic role of a LV marker, podoplanin (PDPN), in predicting the mortality of patients with cirrhosis." (PMID 37304826, 2023). "Collectively, dilated LVs with high PDPN expression in D2-biopsies is a characteristic feature of patients with decompensated cirrhosis." (PMID 37304826, 2023). "LYVE1 (4-fold) and PDPN (9-fold) mRNA levels were elevated in patients with cirrhosis compared to controls (p < 0.0001)." (PMID 37304826, 2023). "Patients with compensated and decompensated cirrhosis displayed a large number of PDPN+ dilated lymphatic channels, consisting of a single layer of endothelial cells in the mucosal and submucosal regions of D2-biopsies." (PMID 37304826, 2023). "Gene expression of LV markers, PDPN (8-fold), and LYVE1 (3-fold) was enhanced in D2-biopsies of cirrhosis patients compared to control (p < 0.0001)." (PMID 37304826, 2023). "Concerning intrahepatic LVs, it is known that there is an increase in the number of dilated D2-40/podoplanin liver LVs and lymphangiogenesis in patients with cirrhosis and portal hypertension, regardless of disease etiology." (PMID 37304826, 2023).
clear cell renal cell carcinoma (2 papers, 2023 to 2024). "It was also observed that PDPN was increased in sinonasal squamous cell carcinoma and clear cell renal cell carcinoma and associated with low rates of patients’ overall survival and disease‐free survival." (PMID 36156321, 2023).
colorectal adenocarcinoma (2 papers, 2021 to 2022). The most common type of colorectal carcinoma. "We first sought to determine if PDPN expression was associated with clinical outcome, focusing on colorectal adenocarcinoma (CRC)." (PMID 34879110, 2021). "The increased podoplanin expression was observed in patients with colorectal adenocarcinoma." (PMID 35902826, 2022).